MALAT1 (metastasis associated lung adenocarcinoma transcript 1)
Diseases named in the same sentence as MALAT1 in open-access papers (continued):
Sharing a sentence is not in itself a finding about the gene and the disease.
psoriasis (9 papers, 2020 to 2025). An autoimmune condition characterized by red, well-delineated plaques with silvery scales that are usually on the extensor surfaces and scalp. "MALAT1 contains the rs619586 polymorphism, which has been identified as a risk locus for psoriasis in the Iranian population, further supporting the functional relevance of this lncRNA in disease pathogenesis." (PMID 40981386, 2025). "Among the identified lncRNAs, some had an already known carcinogenic role, such as H19, growth specific arrest 5 (GAS5), metastasis-associated lung adenocarcinoma transcript 1 (MALAT1), and psoriasis-associated RNA induced by stress (PRINS)." (PMID 35883677, 2022). "There were also reports of genetic variants in MALAT-1 and psoriasis susceptibility evaluated in an Iranian cohort, which demonstrated a greater association of a specific SNP with the risk of psoriasis, opening questions about a potential risk locus for psoriasis in the Iranian population." (PMID 40725772, 2025). "Psoriasis tissues had increased MALAT1 levels; nevertheless, the exact functions require clarification." (PMID 37310201, 2023). "Mechanistically, MALAT1 is upregulated by IL-17, one of the master cytokines in psoriasis." (PMID 40981386, 2025). "Notably, hsa_circ_0004287 reduced the stability of MALAT1, an important immune-suppressive gene in psoriasis." (PMID 37310201, 2023). "Several lncRNAs might act as psoriasis biomarkers and/or therapy targets, such as the IL−22-responsive SPRR2C, psoriasis susceptibility gene PRINS, NF-κB-dependent ANRIL, IL−17A-promoting H19, and the innate immune response-related HOTAIR and MALAT1." (PMID 37310201, 2023). "Furthermore, MALAT1 negatively regulates the innate immune responses in psoriasis." (PMID 37310201, 2023). "The expression of lncRNA metastasis-associated lung adenocarcinoma transcript 1 (MALAT-1) expression is significantly increased in the lesional skin, non-lesional skin, and serum of psoriasis patients, and MALAT-1 dysregulation depends on nuclear factor kappa-B (NF-κB)." (PMID 37762693, 2023).
squamous cell carcinoma (9 papers, 2013 to 2023). A carcinoma arising from squamous epithelial cells. "detected the expression of MALAT1 and found that high MALAT1 expression was associated with poor prognosis for squamous cell carcinoma." (PMID 37526759, 2023). "Considering the different characteristics of these two major subtypes of NSCLC, the lncRNA MALAT1 may induce tumor metastasis through different mechanisms between adenocarcinoma and squamous cell carcinoma." (PMID 28253859, 2017). "Subsequently, samples from Stage I patients suffering from adenocarcinoma or squamous cell carcinoma were analyzed by qRT-PCR, confirming that expression levels of MALAT1 were significantly higher in metastasizing adenocarcinomas compared to non-metastasizing ones." (PMID 23455466, 2013).
acute kidney injury (8 papers, 2018 to 2024). Sudden and sustained deterioration of the kidney function characterized by decreased glomerular filtration rate, increased serum creatinine or oliguria. "In LPS-induced acute kidney injury, silencing MALAT1 elevates the expression of miR-146a, leading to repression of the pro-inflammatory nuclear factor-κB (NF-κB) pathway and its downstream transcription factors." (PMID 32315984, 2020). "Previous studies have found that MALAT1 upregulation can inhibit cell proliferation in acute kidney injury and neonatal respiratory distress syndrome, promote cell apoptosis, and proinflammatory cytokine expression." (PMID 33117815, 2020). "We first assessed the concentration of Malat1 in plasma samples of patients with acute kidney injury (AKI) and found it to be highly increased compared to healthy controls." (PMID 29467431, 2018).
myocardial ischemia (8 papers, 2018 to 2025). A disorder of cardiac function caused by insufficient blood flow to the muscle tissue of the heart. "Metastasis-associated lung adenocarcinoma transcript 1 (MALAT1) is a lncRNA upregulated in response to hypoxia and myocardial ischemia." (PMID 30227648, 2018). "Recent pieces of evidence have revealed that MALAT1 holds a substantial significance in the growth, progress and management of cardiovascular diseases, especially in cases of myocardial ischemia and reperfusion damage." (PMID 39171328, 2024). "To conclusion, MALAT1's diverse role in myocardial ischemia and damage disorders places it not only as an important biomarker for disease development and prognosis, but also as a viable target for therapeutic approaches." (PMID 39171328, 2024). "The expression of miR-206 was markedly downregulated in the heart tissue of rats with myocardial ischemia–reperfusion injury, and the overexpression of lncRNA MALAT1 significantly suppressed miR-206 expression." (PMID 37730550, 2023). "Similarly, silenced MALAT1 reduced myocardial ischemia-reperfusion injury in rat cardiomyocytes by regulating the miR-135a-5p/HIF1AN axis." (PMID 36032150, 2022).
pancreatic ductal adenocarcinoma (8 papers, 2015 to 2024). An infiltrating adenocarcinoma that arises from the epithelial cells of the pancreas. "On the one hand, the high expression of lnc MALAT1 in pancreatic ductal adenocarcinoma inhibits the expression of miR‐200c‐3p27." (PMID 38270295, 2024). "On the one hand, miR‐200c‐3p can mediate the silencing of MALAT1, which plays a significant role in the migration and invasion of pancreatic ductal adenocarcinoma and can be used as a prognostic indicator." (PMID 38270295, 2024). "In human pancreatic ductal adenocarcinoma tissues, MALAT1 expression positively correlates with the oncogenic ZEB1 and negatively correlates with miR-200c-3p, and MALAT1 is expressed at higher levels in metastatic compared with localized tumors." (PMID 32174966, 2020). "Multivariate analysis reveals that high levels of MALAT1 expression in human pancreatic ductal adenocarcinoma tissues independently predict poor patient survival." (PMID 32174966, 2020). "We have previously found that the metastasis-associated lung adenocarcinoma transcript 1 (MALAT-1) promotes cell proliferation and metastases in pancreatic ductal adenocarcinoma (PDAC)." (PMID 30352575, 2018). "These mice rapidly develop pancreatic ductal adenocarcinoma-like tumors and were crossed with MALAT-1-/- mice." (PMID 29389953, 2018). "The aim of this study was to investigate the role of MALAT1 in pancreatic ductal adenocarcinoma." (PMID 28701723, 2017). "MALAT1 is expressed at higher levels in pancreatic ductal adenocarcinoma (PDAC) tissues than in nontumour tissues and in metastatic PDAC than in localized tumours." (PMID 28701723, 2017).
tongue squamous cell carcinoma (8 papers, 2016 to 2025). A squamous cell carcinoma that arises from the tongue. "In addition, two studies provided experimental supports for the association of MALAT1 and tongue squamous cell carcinoma." (PMID 32024523, 2020). "It has been reported that the expression of lncRNA MALAT1 was upregulated in tongue squamous cell carcinoma (TSCC) and was related to cervical lymph node metastasis." (PMID 32185124, 2020). "MALAT1 showed abnormally high expression in breast cancer, liver cancer, gastric cancer, and tongue squamous cell carcinoma, which promoted the migration and proliferation of cancer cells and affected the drug resistance of cancer cells." (PMID 32185124, 2020).
acute respiratory distress syndrome (7 papers, 2020 to 2023). Progressive and life-threatening pulmonary distress in the absence of an underlying pulmonary condition, usually following major trauma or surgery. "MALAT1 targeted miR-150-5p to exacerbate acute respiratory distress syndrome by upregulating ICAM-1 expression." (PMID 34012919, 2021). "It has actually been noted that lnc-MALAT1 was upregulated in acute respiratory distress syndrome (ARDS), and the high lnc-MALAT1 expression was independently related to a higher risk of ARDS as well as COPD." (PMID 34604205, 2021). "For example, MALAT1 was reportedly related to acute respiratory distress syndrome related to lung injury, downregulation of SNHG14 had protective effects against LPS-induced ALI, and CASC2 improved ALI by reducing lung epithelial cell apoptosis." (PMID 33506021, 2021). "In another study lnc-MALAT1 expression was increased in acute respiratory distress syndrome (ARDS) patients compared to non-ARDS patients (AUROC: 0.674)." (PMID 34991675, 2022).
aneurysm (7 papers, 2018 to 2024). Bulging or ballooning in an area of an artery secondary to arterial wall weakening. "The results demonstrated a significant upregulation of MALAT-1 in IA patients, and its elevated levels were associated with both the rupture of the aneurysms and unfavorable clinical outcomes." (PMID 38542406, 2024). "However, in the presence of aneurysm-associated alleles MALAT1 is more closely associated with heterochromatin and regions of dense H3K27 trimethylation." (PMID 29520069, 2018). "In other cellular contexts, Gata4 has been shown to promote induction of the pro-inflammatory senescence-associated secretory phenotype (SASP) as well as transcription of the lncRNA Malat1, which promotes aneurysm development in other mouse models." (PMID 38883722, 2024). "The expression of MALAT1 and H19 is significantly increased in atherosclerotic lesions and aneurysm tissues." (PMID 37568514, 2023). "Targeting HDAC9-BRG1-MALAT1 complex by deletion of Malat1 or Hdac9 in vivo restores contractile protein gene expression, improves aortic mural architecture, and inhibits experimental aneurysm growth in Fbn1C1039G/+ (Marfan syndrome) mouse model." (PMID 32241300, 2020). "Disruption of Malat1 or Hdac9 restores contractile protein expression, improves aortic mural architecture, and inhibits experimental aneurysm growth." (PMID 29520069, 2018). "Previously we demonstrated decreased MMP activation in our cellular models of aneurysm after silencing of the MALAT1 expression." (PMID 29520069, 2018). "FISH results suggested that the level of Malat1 in AAA tissue was much higher than the physiological baseline in the AA segment, particularly in the aneurysm part (P < 0.01, one-way ANOVA)." (PMID 35473929, 2022). "In the AngII-induced mouse model, we detected the expression of Malat1 in AAA, including in both vessel and aneurysm parts." (PMID 35473929, 2022). "In SMCs of aortas from an aneurysm mouse model, increased expression and colocalization of HDAC9, BRG1, and MALAT1 was found and deletion of MALAT1 or HDAC9 restored the contractile protein expression and inhibited aneurysm growth." (PMID 30893946, 2019).
bronchopulmonary dysplasia (7 papers, 2017 to 2025). Bronchopulmonary dysplasia is a chronic respiratory disease that results from complications related to lung injury during the treatment of infant acute respiratory distress syndrome in low-birth-weight premature infants or from abnormal lung development in older infants. "Although the loss of MALAT1 does not affect lung development, a previous study indicated that the upregulation of MALAT1 may protect preterm infants with bronchopulmonary dysplasia by inhibiting apoptosis." (PMID 40721598, 2025).
cardiac hypertrophy (7 papers, 2018 to 2023). "Previous research identified MALAT1 as most significantly dysregulated during hypoxia and showed that MALAT1 expression is actually driven via hypoxia-inducible factor 1α, and the silencing of MALAT1 expression decreases the severity of heart hypertrophy." (PMID 34604205, 2021). "The results disclosed that XIST, MALAT1 and H19 possibly regulated other miRNAs involved in cardiac hypertrophy, such as miR-15b, miR-19b and miR-29b in our research." (PMID 34362365, 2021). "The role of Malat1 in cardiac hypertrophy is still under debate." (PMID 33732733, 2021). "However, the low expression of MALAT1 may promote myocardial hypertrophy." (PMID 37109540, 2023). "In addition to validating known EZH2-binding ncRNAs (e.g., Gas5, Meg3, and Malat1), our findings reveal a large panel of novel ncRNAs involved in the dynamic regulation of the EZH2 function during AngII-induced cardiac hypertrophy." (PMID 33732733, 2021). "Absence of Malat1 did not affect cardiac hypertrophy upon pressure overload." (PMID 29467431, 2018).
colon adenocarcinoma (7 papers, 2020 to 2026). "Both variants were enriched in the nuclear/nuclear envelope (NE) fraction of all five cell types tested, thus agreeing with previous data in colon adenocarcinoma cells, and resembling the strictly nuclear lncRNA MALAT1, serving as a positive control." (PMID 41556346, 2026). "Most interestingly, we identified two MALAT1-dependent novel molecules, ZNF638 and SENP8, that are associated with significant alterations in colon adenocarcinoma patients’ overall survival and disease-free survival." (PMID 37325561, 2023). "Data indicated that MALAT1 was significantly upregulated in colon adenocarcinoma (COAD) in comparison with normal samples." (PMID 33344634, 2020). "The Oncomine boxed plot revealed significantly up-regulated MALAT1 in colon adenocarcinoma (COAD) tissues using GEO database (GSE5206)." (PMID 32209115, 2020). "In addition, two of the MALAT1 targets shared across the small intestine and colon, ZNF638 and SENP8, are associated with a change in hazards ratio for overall survival and disease-free survival in human colon adenocarcinoma patients." (PMID 37325561, 2023).
gastric adenocarcinoma (7 papers, 2017 to 2025). "According to the research, MALAT-1 was substantially expressed in both gastric adenocarcinoma cell lines and the serum of individuals with the disease." (PMID 38511067, 2024). "The MALAT-1/miR-181a-5p/AKT3 axis plays a critical role in the promotion of gastric adenocarcinoma, as shown by this research." (PMID 38511067, 2024). "Using the AKT antagonist ipatasertib or overexpressing miR-181a-5p had comparable effects to MALAT-1 knockdown, highlighting the significance of the MALAT-1/miR-181a-5p/AKT3 axis in the development of gastric adenocarcinoma." (PMID 38511067, 2024). "Metastasis-associated lung adenocarcinoma transcript 1 (MALAT1), also known as non-coding nuclear-enriched abundant transcript 2 (NEAT2), promotes gastric adenocarcinoma through the MALAT1/miR-181a-5p/AKT3 axis." (PMID 37998329, 2023). "Following the publication of ‘MALAT1 promotes gastric adenocarcinoma through theMALAT1/miR-181a-5p/AKT3 axis’, the Editorial team have concerns regarding thevalidity of the data used in this study." (PMID 37651290, 2023). "High levels of MALAT1 are detected in the serum in people with gastric adenocarcinoma." (PMID 37998329, 2023). "AKT3 protein levels rise as a result of MALAT-1 and AKT3 competition for miR-181a-5p binding, which eventually aids gastric adenocarcinoma cell proliferation and survival." (PMID 38511067, 2024). "We undertook to validate MALAT1, which has not been previously reported as an lncRNA involved in gastric adenocarcinoma." (PMID 28077118, 2017).
gestational diabetes (7 papers, 2018 to 2025). Carbohydrate intolerance first diagnosed during pregnancy. "For example, the circulating levels of the lncRNA metastasis associated lung adenocarcinoma transcript 1 (MALAT1) were found to be increased in women with GDM (gestational diabetes mellitus)." (PMID 32545342, 2020). "Gestational diabetes was characterized by the elevation of MALAT1." (PMID 40870007, 2025). "It was reported that lncRNA MALAT1 was upregulated in gestational diabetes patients." (PMID 36297381, 2022).
head and neck cancer (7 papers, 2013 to 2023). A primary or metastatic malignant neoplasm affecting the head and neck. "In contrast, the tobacco smoking is the most-established risk factor for head and neck cancer in the Western society, suggesting the various pathogenic mechanisms in the different ethnic cohorts may lead the different MALAT1 expression status." (PMID 34268119, 2021). "Our findings highlight the critical role of lncRNA MALAT1 for tumorigenesis and progression of head neck cancer cells." (PMID 31792655, 2020). "Our previous studies have illuminated the critical roles of P65 and β-catenin in head and neck cancer, so we explored whether MALAT1 promoted HNSCC progression by regulating these two pathways." (PMID 36813772, 2023). "MALAT1 was shown as a circulating biomarker of head and neck cancer." (PMID 33015029, 2020). "Our findings imply that MALAT1 may be employed as a clinical prognostic biomarker for head and neck cancer progression." (PMID 31792655, 2020).